ABI1 (abl interactor 1)
Diseases named in the same sentence as ABI1 in open-access papers (continued):
Sharing a sentence is not in itself a finding about the gene and the disease.
ovarian carcinoma (11 papers, 2012 to 2024). A malignant neoplasm originating from the surface ovarian epithelium. "EMT in ovarian cancer cells is dependent on RAC1 activation through the SOS1/EPS8/ABI1 complex, associated with increased MEK-ERK and SRC activation." (PMID 39354505, 2024). "In sum, ABI1 is essential to promote metastasis in ovarian cancer through SOS1/EPS8/ABI1 complex activation, linked to regulations of inflammatory signaling and cytoskeletal reorganization." (PMID 39354505, 2024). "A study of 46 patients with epithelial ovarian cancer found that ABI1 protein and mRNA expression are higher in cancerous tissue than in non-cancerous tissue." (PMID 39354505, 2024). "ABI1 is posited to be an independent prognostic factor – as the tumor promoting gene – in epithelial ovarian cancer progression." (PMID 39354505, 2024). "Similar to its metastasis-promoting role in ovarian cancer, ABI1 likely promotes metastasis in HCC as an essential component of the ABI1/EPS8L3/SOS1 complex." (PMID 39354505, 2024). "ABI1 has been cited in several cancer types, such as ovarian cancer, hepatocellular carcinoma, and colorectal carcinoma." (PMID 34967509, 2022). "ABI1 has been linked to the EMT induction in prostate carcinogenesis, ovarian cancer metastasis, and neuroblastoma development, invasion, and metastasis in several investigations." (PMID 34872548, 2021). "Plasmids containing various regions of HA-tagged ABI1 were co-transfected into ovarian cancer cells with Flag-tagged SOS1 or Myc-tagged EPS8." (PMID 31488087, 2019). "We aimed to develop inhibitory short peptides that can prevent protein interactions of SOS1/EPS8/ABI1 tri-complex, a key component essential for ovarian cancer metastasis." (PMID 31488087, 2019). "The formation of endogenous SOS1/EPS8/ABI1 tri-complex was detected in the event of LPA-induced ovarian cancer cell invasion." (PMID 31488087, 2019). "Since the integrity of SOS1/EPS8/ABI1 is essential for LPA-induced ovarian cancer metastasis, these inhibitory short peptides are expected to inhibit the invasion of cancer cells." (PMID 31488087, 2019). "In addition, some scholars have found that the presence of the SOS1/EPS8/ABI1 complex correlated well to the continuous epithelial–mesenchymal transition (EMT) characteristics of ovarian cancer cells, and an intact complex is required for this procedure." (PMID 34825509, 2021). "Therefore, the metastatic potential of ovarian cancer is closely related to the integrity of the SOS1/EPS8/ABI1 complex." (PMID 34825509, 2021). "Our previous study demonstrated that LPA could stimulate Rac activation, cytoskeleton reorganization, and ovarian cancer cell migration through a signaling pathway consisting of Ras-SOS1/EPS8/ABI1 tri-complex." (PMID 31488087, 2019). "The specific involvement of EPS8/ABI1/SOS1 tri-complex in ovarian cancer metastasis suggests that this tri-complex-targeted drugs may have less effects on non-cancer tissues than on cancer tissues." (PMID 31488087, 2019). "Its tri-complex relationship with SOS1 and ABI1 has been found to be an essential component for lysophosphatidic acid-stimulated cell migration and Rac activation, which has been found to play an important role in ovarian cancer metastasis." (PMID 24367505, 2013). "Our finding of Abi1 overexpression during the development of invasive carcinomas is comparable to findings made in ovarian cancer, where coexpression of the trimeric Abi1/SOS1/Eps8-complex is a prerequisite for Rac-dependent ovarial cancer cell motility upon lysophosphatidic acid (LPA)-stimulation." (PMID 22808230, 2012). "ABI1 expression level may also have prognostic significance in ovarian cancer." (PMID 39354505, 2024). "Blocking interaction between ABI1 and EPS8 in vivo suppresses LPA-induced invasion and metastasis of ovarian cancer cells." (PMID 39354505, 2024).
ovarian carcinoma (continued). "The integrity of SOS1/EPS8/ABI1 tri-complex may determine ovarian cancer metastatic potentials, as silencing any member of SOS1/EPS8/ABI1 tri-complex is sufficient to diminish the migration and metastatic colonization of ovarian cancer cells." (PMID 31488087, 2019). "With the aid of a well-established peritoneal seeding model, we demonstrated that the presence of SOS1/EPS8/ABI1 tri-complex correlated well to the metastatic potential of ovarian cancer cells, and an intact SOS1/EPS8/ABI1 tri-complex is required for Rac activation." (PMID 31488087, 2019).
prostate carcinoma (9 papers, 2015 to 2024). A carcinoma that arises from epithelial cells of the prostate gland. "Low ABI1 expression is detected in the LNCaP human prostate cancer cell line, and ABI1 mutations are observed in prostate cancers." (PMID 39354505, 2024). "ABI1 dysregulation has been implicated in several cancers, such as breast, brain, colon, stomach, ovarian, and prostate cancers." (PMID 34967509, 2022). "It has been indicated that low ABI1 expression was associated with metastasis and shorter survival of prostate cancer patients." (PMID 34944712, 2021). "ABI1 is associated with 10p deletions in prostate cancer, along with ABI1 mutations and deletions being identified within the gene itself." (PMID 31530281, 2019). "In addition, the prostate cancer cell line LNCaP has a mutation in ABI1; re-expression of ABI1 inhibits prostate tumor xenograft growth." (PMID 31530281, 2019). "Moreover, there were striking aberrations in the expression of alternative spliced variants of Abi1 in prostate cancer cell lines and tumor organoids identified here." (PMID 31530281, 2019). "Here, we investigated the mechanistic roles for ABI1 loss in prostate cancer progression." (PMID 31530281, 2019). "In addition, we previously implicated ABI1 (SSH3BP1) as a putative tumor suppressor in prostate cancer and have demonstrated that disruption of Abi1 in the mouse prostate leads to prostatic intraepithelial neoplasia (PIN), but not to invasive prostate cancer." (PMID 25906751, 2015). "Additionally, a study of 505 patients with prostate cancer found that low ABI1 expression is associated with increased cancer recurrence, metastasis, and death, linked to activation of epithelial-mesenchymal transition (EMT) pathways and non-canonical WNT signaling." (PMID 39354505, 2024). "ABI1 was recently shown to regulate the transcriptional activity of AR in prostate cancer cells and can prove to be a novel and effective drug target for AR+ TNBC cells." (PMID 38067367, 2023). "Our previous studies identified the loss of heterozygosity in ABI1 gene locus, however, the mechanism of ABI1 role as a tumor suppressor in prostate cancer is poorly understood." (PMID 31530281, 2019). "To validate this observation, we analyzed ABI1 expression in large cohort of prostate cancer patients (n = 505)." (PMID 31530281, 2019). "Interestingly, this is inconsistent with the earlier discussed role of ABI1 as a tumor suppressor in prostate cancer, in which decreased expression leads to decreased E-cadherin expression and inhibition of canonical WNT signaling." (PMID 39354505, 2024). "For example, ABI1 has been reported to function as a tumor suppressor in prostate cancer." (PMID 37746268, 2023). "Mutations of ABI1 in prostate cancer are not very common but are evident in tumor sequencing data and PCa cell lines." (PMID 31530281, 2019). "Moreover, ABI1 is downregulated in castration-resistant prostate cancer, thus indicating that it might be important in tumor progression." (PMID 31530281, 2019). "ABI1 can also inhibit EMT in prostate cancer by suppressing FYN-signal transducer and activator of transcription 3 (STAT3) activation by non-canonical WNT signaling through a high affinity interaction between the FYN SH2 domain and ABI1 pY421." (PMID 39354505, 2024). "For example, by activating the EMT and non-canonical WNT signaling, ABI1 can drive the tumorigenesis of prostate cancer." (PMID 34195183, 2021). "To better understand the role of ABI1 as a tumor suppressor in prostate cancer and define ABI1-regulated pathways, we sought to generate a prostate epithelial cell line lacking ABI1 gene expression." (PMID 31530281, 2019). "ABI1, a member of WAVE complex and actin cytoskeleton regulator and adaptor protein, acts as tumor suppressor in prostate cancer but the role of ABI1 in EMT is not clear." (PMID 31530281, 2019).
colorectal cancer (8 papers, 2012 to 2024). A primary or metastatic malignant neoplasm that affects the colon or rectum. "In 56 primary human colorectal carcinoma samples, we found overexpression of Abi1 in 39% at the invasive edge of the tumour, associated with an infiltrative phenotype and high-grade tumour cell budding (p = 0.001)." (PMID 24913355, 2014). "In colorectal cancer cell lines, there was strong expression of Abi1 in lysates from KRAS-mutated cells, but only a very faint signal in lysate from BRAF-mutated cells." (PMID 22808230, 2012). "We immunohistochemically analyzed Abi1 protein expression in 126 tissue specimens from 95 patients and in 5 colorectal carcinoma cell lines with different mutation status by western immunoblotting." (PMID 22808230, 2012). "Further underlining apparently contrasting roles of ABI1 in tumor regulation, a study of 95 colorectal cancer patients found that ABI1 expression is positively correlated with metastasis and was overexpressed in inflammatory mucosa, sessile serrated polyps, adenomas, and tubular adenomas." (PMID 39354505, 2024). "In this study, we analyzed the expression pattern of Abi1 in colonic mucosa with and without inflammation, in colonic precursor lesions, colorectal carcinoma and colorectal cancer metastasis and correlated Abi1 expression with the respective KRAS/BRAF mutation status of each lesion." (PMID 22808230, 2012). "Furthermore, we analyzed Abi1 expression status in three widely-used colorectal carcinoma cell lines with known mutation status as well as in two colorectal carcinoma cell lines that have been previously established by our work group." (PMID 22808230, 2012). "ABI1 is also upregulated by TNFα treatment in colorectal cancer cell lines, and ABI1 overexpression is abolished by PI3K inhibitor treatment in KRAS-transfected cells." (PMID 39354505, 2024). "ABI1-212 is decreased in colorectal cancer cell lines and tissues, while full length ABI1 is elevated." (PMID 39354505, 2024). "ABI1 isoforms are differentially downregulated in esophageal, gastro-intestinal, and colorectal cancers." (PMID 39354505, 2024). "While ABI1 is also described as a tumor promoter, this section describes its reported role as a tumor suppressor in prostate, blood, brain, gastric, and colorectal cancers." (PMID 39354505, 2024). "ABI1-212 is a dominant-negative form of full-length ABI1 in colorectal cancer cells, competing with full length ABI1 to bind WAVE2 and phosphorylated full-length ABI1 to inhibit cell adhesion and migration." (PMID 39354505, 2024). "(A) T1 colorectal cancer (CRC) samples from a set of 47 cases were used to verify the abundance of ABI1, ITPR2, RHOT2, ATAD2, and ISLR." (PMID 37158593, 2023). "Abnormally expressed and/or phosphorylated Abelson interactor 1 (ABI1) participates in the metastasis and progression of colorectal cancer (CRC)." (PMID 34031495, 2021). "Our data indicate that phosphorylated Abi1 contributes to the invasive properties of colorectal cancer." (PMID 24913355, 2014). "CHD1 colorectal carcinoma cells are positive for Abi1, hnRNP K and Laminin5γ2 in Western immunoblotting." (PMID 24913355, 2014). "The c-Abl substrate abelson interactor 1 (Abi1) is a key regulator of actin reorganization and upregulated in colorectal carcinoma." (PMID 24913355, 2014). "Among colorectal carcinoma metastases, Abi1 immunohistochemistry showed the same intense cytoplasmic staining pattern in almost all examined samples." (PMID 22808230, 2012). "Furthermore, in a study of 56 colorectal cancer samples, ABI1 positively correlates with an invasive phenotype and is upregulated at the invasive edge." (PMID 39354505, 2024). "Here, we investigated the role of Abi1 in relation to invasive properties in colorectal cancer." (PMID 24913355, 2014). "Consistent with that, we could show increased Akt phosphorylation and overexpression of Abi1 upon TNFalpha stimulation in KRAS wild-type colorectal carcinoma cells." (PMID 22808230, 2012).
colorectal cancer (continued). "Finally, we investigated the effect of transfection with either KRAS wild-type or KRAS G12D as well as TNFalpha stimulation and Wortmannin treatment on Abi1 expression in KRAS wild-type colorectal carcinoma cells." (PMID 22808230, 2012). "However, in CHD-1 colorectal carcinoma cells carrying the KRAS G13D mutation, we could show slight nuclear Abi1 positivity in immunofluorescence microscopy." (PMID 22808230, 2012). "To further confirm these results, we used two colorectal carcinoma cell lines (CHD-1 and HDC-9) with yet unknown mutation status that have been established by our work group in the 1990s and found that the cell line overexpressing Abi1 (CHD-1) carries an activating mutation in codon 13 of KRAS." (PMID 22808230, 2012). "Furthermore, we examined the effect of STI571 on Abi1 phosphorylation, metalloproteinase secretion, ECM degradation and colorectal cancer cell invasion." (PMID 24913355, 2014). "Accordingly, HDC9 KRAS/BRAF wild-type colorectal carcinoma cells - that weakly express Abi1 - display high levels of E-cadherin and no cleavage of Laminin5 indicated by a single y2′ band migrating at 100–105 kD." (PMID 24913355, 2014). "Accordingly, overexpression of interaction partners of Abi1 (hnRNP K, N-WASP and WAVE2) has also been previously reported in colorectal carcinoma and CRC metastasis." (PMID 24913355, 2014).
gastric cancer (5 papers, 2012 to 2024). A primary or metastatic malignant neoplasm involving the stomach. "Furthermore, an ABI1 exon skipping event in gastric cancers is associated with decreased overall and disease-free survival." (PMID 39354505, 2024). "Decreased ABI1 expression is also more frequently observed in gastric cancer, correlated with decreased survival time and five-year-survival rate." (PMID 39354505, 2024). "However, their results show a different extent of downregulation among the Abi1 isoforms and among different cancers, with the results from colon cancer being not as clear-cut as the results from stomach cancer." (PMID 22808230, 2012).
myeloproliferative neoplasm (4 papers, 2020 to 2026). A clonal hematopoietic stem cell disorder, characterized by proliferation in the bone marrow of one or more of the myeloid (i.e., granulocytic, erythroid, megakaryocytic, and mast cell) lineages. "Loss of mammalian Abi1 causes myeloproliferative neoplasm; however, little is known about how the Abi family of actin-regulatory proteins regulates blood cell homeostasis." (PMID 41474627, 2026). "ABI1 loss in hematopoietic stem/progenitor cells was previously shown to be associated with development of a myeloproliferative neoplasm." (PMID 36635880, 2023). "Although disruption of mammalian Abi1 has been implicated in the pathogenesis of myeloproliferative neoplasm and acute myeloid leukemia, it is unknown how actin-regulatory Abi proteins regulate normal hematopoiesis." (PMID 41474627, 2026). "Furthermore, bone marrow–specific knockout of Abi1 in mice causes myeloproliferative neoplasm, supporting a tumor suppressor function." (PMID 41474627, 2026). "Moreover, while the BM-specific Abi1 deficiency leads to myeloproliferative neoplasm, it impairs B cell development in mice." (PMID 32276588, 2020). "As mentioned, ABI1 is also downregulated in patients with myeloproliferative neoplasms (MPN), a class of blood cancers characterized by abnormal expansion of the myeloid blood compartment." (PMID 39354505, 2024). "Recently, we found evidence of decreased ABI1 expression in hematopoietic stem/progenitor cells in patients with myeloproliferative neoplasm (MPN)." (PMID 36635880, 2023).
neuroblastoma (4 papers, 2019 to 2024). Neuroblastoma (NB) is the most common solid, extracranial childhood tumor. "In neuroblastoma, siRNA against ABI1 results in more metastatic cells, and ABI1 overexpression reduces neuroblastoma cell migration." (PMID 39354505, 2024). "Together, ABI1 can repress growth and metastasis of neuroblastoma cells through suppression of mechanisms that promote activation of downstream effectors including ABL1, and this can be regulated on the transcriptional level." (PMID 39354505, 2024). "The 3’-untranslated region (UTR) of ABI1 is targeted by miR-181a and miR-181b, resulting in decreased ABI1 expression and increased neuroblastoma growth and metastasis." (PMID 39354505, 2024).
adenoma (3 papers, 2012 to 2024). A neoplasm arising from the epithelium. "Abi1 was strongly expressed in the mucosal cytoplasm of sessile serrated polyps and adenomas (SSP/A), traditional serrated adenomas (TSA) and tubular adenomas (TbA) compared to healthy mucosa, wild-type and BRAF-mutated HPP." (PMID 22808230, 2012). "Furthermore, Abi1 is overexpressed in inflammatory mucosa, sessile serrated polyps and adenomas, tubular adenomas, invasive CRC and CRC metastasis when compared to healthy mucosa and BRAF-mutated as well as KRAS wild-type hyperplastic polyps." (PMID 22808230, 2012). "Our own group investigated the role of Abi1 in CRC and showed upregulation of Abi1 during the adenoma-carcinoma sequence of colorectal carcinogenesis as well as in KRAS-mutant hyperplastic polyps with constitutive activation of EGFR signaling pathway." (PMID 26345720, 2015).
asthma (3 papers, 2020 to 2022). "Loss-of-function studies suggest that Abi1 contributes to aberrant HASM cell proliferation and asthma phenotype in a murine model of asthma." (PMID 36078171, 2022). "The proteins that are regulated by LPS and were previously shown to be implicated in asthma and in ASM proliferation also include the upregulation of matrix-metalloproteinase-1 (MMP-1) and Abelson interactor 1 (Abi1) and the downregulation of insulin-like growth factor-binding protein 2 (IGFBP-2)." (PMID 36359743, 2022). "In this study, Abi1 plays a role in regulating airway smooth muscle migration, which raises the possibility that Abi1 may participate in the development of airway smooth muscle thickening in asthma." (PMID 32606387, 2020).
colon cancer (3 papers, 2012 to 2023). "It has previously been reported that low levels of ABI1 and high levels of ADAT2 or ISLR, result in an increase in extracellular matrix (ECM) degradation, migration, and cell invasion in colon cancer." (PMID 37158593, 2023).
glioblastoma (3 papers, 2015 to 2024). The most malignant astrocytic tumor (WHO grade IV). "CRK pY251, identified as a marker for aggressive glioblastoma correlated with high invasion and poor survival outcome, is negatively regulated by ABI1." (PMID 39354505, 2024). "Similarly, copy number alteration analysis of datasets from Beroukhim and colleagues and TCGA database (normal = 321, glioblastoma = 472) indicate that Abi1 gene copy number is significantly reduced in GBM compared to normal tissue." (PMID 26473374, 2015). "Glioblastoma migration affected by WAVE2, SKAP2, cortactin, and FYN was also discussed earlier in relation to ABI1 and ABL1, linking EGFR and SFK signaling directly to ARP2/3-mediated actin polymerization." (PMID 39354505, 2024).
hepatocellular carcinoma (3 papers, 2019 to 2024). A malignant tumor that arises from hepatocytes. "ABI1 upregulation in hepatocellular carcinoma (HCC) also positively correlates with tumor size, stage, number, and encapsulation." (PMID 39354505, 2024).